CDK6 (cyclin dependent kinase 6)
Diseases named in the same sentence as CDK6 in open-access papers (continued):
Sharing a sentence is not in itself a finding about the gene and the disease.
tumor (continued). "Furthermore, our animal experiments and studies using clinical samples showed an inverse correlation between miR-214 levels and expression of E2F2, CDK3, and CDK6, as well as tumor progression." (PMID 26498144, 2016). "Furthermore, many studies show that specific inhibitors of CDK6 have anti-tumor effects in various malignancies." (PMID 27230400, 2016). "Having found that CDK4 but not CDK6 could regulate MET and the phenotype of the cells, we next investigated the potential role of CDK6 in regulating cancer stemness in TNBC and its potential association with tumor progression and outcomes." (PMID 27759034, 2016). "In addition to the induction of p16INK4a, CDK6 also induces transcription of vascular endothelial growth factor A (VEGFA), a known angiogenic factor and tumor promoter, thereby linking two hallmark cancer features." (PMID 25914884, 2015). "Finally, in vitro investigation confirmed that miR-211 is a tumor suppressor that controls Cyclin D1 and CDK6 expression." (PMID 25889927, 2015). "Our results demonstrate that miR-211 is a tumor suppressor that controls expression of Cyclin D1 and CDK6, and that its downregulation results in overexpression of Cyclin D1 and CDK6 which increases proliferation ability of EOC cells to proliferate compared to normal cells." (PMID 25889927, 2015). "In addition, CDK6 was shown to be regulated by miR-129, which functioned as a potential tumor suppressor." (PMID 25652781, 2015). "Additionally, survival probabilities were significantly lower in tumor with high expression of cdk2 (p = 0.006), cdk4 (p = 0.003) or cdk6 (p = 0.045)." (PMID 26029996, 2015). "Collectively, these data link high CDK6 expression to enforced tumor angiogenesis." (PMID 23948297, 2013). "In 20 sets of tissue samples collected from different brain regions, expression of the CDK6 gene was upregulated significantly in tumor core samples (P = 0.0042) relative to peripheral normal brain, although expression decreased progressively in samples taken more distally." (PMID 23594394, 2013). "Accordingly, the requirement for p16INK4a may be regarded as an internal safeguard that needs to be overcome to allow CDK6 to exert its tumor-promoting function." (PMID 23948297, 2013). "The tumor suppressor activity of miR-29 may be achieved through targeting cell cycle regulators and oncogenes such as Cdk6, DNA methyltransferase 3A (DNM3A) and 3B (DNMT3B), Mcl-1, and Tcl1A." (PMID 23431463, 2013). "Meanwhile, among the target genes for miR-195 and miR-497 identified in the present study, top four target genes, CCNE1, CDC25A, CDK4 and CDK6, frequently upregulated in a tumor-specific manner only showed slight inverse correlation with these miRNAs in HCC tumors." (PMID 23544130, 2013). "Moreover, target genes frequently upregulated in HCC in a tumor-specific manner, such as CDK6, CCNE1, CDC25A and CDK4, showed an inverse correlation in the expression of miR-195 and miR-497, and their targets." (PMID 23544130, 2013). "Furthermore, CDK6 is expressed more abundantly in the tumor core than in marginal or peripheral regions." (PMID 23594394, 2013). "These experiments are in line with a tumor-suppressing function of CDK6." (PMID 23948297, 2013). "While these experiments show the contribution of CDK6 for cytokine-inducible p65 Ser536 phosphorylation, it was also of interest to investigate whether CDK6 contributes to constitutive p65 phosphorylation as it occurs for example in tumor cells." (PMID 23300567, 2012). "Strong evidence exists supporting a tumor suppressor function for miR-33a via repression of proto-oncogene Pim-1 and inhibition of expression of cyclin-dependent kinase 6 (CDK6) and cyclin D1 (CCDN1), both of which results in reduced cellular proliferation and cell-cycle progression." (PMID 22857597, 2012).
tumor (continued). "By luciferase assay, miR-124-1 has been shown to downregulate CDK6 translation by binding on the 3′ untranslated region (3′ UTR) of the CDK6 mRNA, and also reduce the retinoblastoma protein phosphorylation, thereby demonstrating the tumour suppressor role of miR-124-1." (PMID 21544199, 2011). "It has been shown that CDK4/CDK6 inhibitors could have an essential role in tumor growth." (PMID 40075679, 2025). "Additionally, the relative and absolute expression levels of CDK4 and CDK6, along with factors within the tumor microenvironment, may offer further insights into treatment responsiveness." (PMID 40282469, 2025). "Moreover, the inhibition of CDK4/CDK6 has been shown to effectively reduce MM tumor burden." (PMID 39664374, 2024). "As nude mice lack mature T cells but still have other immune cells, we investigated whether other immune cells such as NK might be involved in suppressing tumor growth.WT or Cdk6−/− tumor cells were subcutaneously implanted to NSG mice, which lack mature T cells, B cells and NK cells." (PMID 37833461, 2023). "Significantly, in the early stages of tumour development, both NFKB1/RELA and PIEZO1 displayed heightened expression levels, paralleled by similar kinetic trends of proliferation‐associated genes such as CDK6, CCND1 and CCND3, as unveiled by functional pseudotime analysis of the scRNA‐seq dataset." (PMID 37983931, 2023). "Furthermore, our current findings suggest that CDK6 may through regulating the cell cycle of tumor cells, in addition to modulating immune checkpoint expression and immune cell infiltration in tumors to exert its oncogenic effects." (PMID 36457244, 2023). "Furthermore, inhibition of CDK6 repressed tumor enlargement in the in vivo lung xenograft model." (PMID 37529110, 2023). "Furthermore, JQ1-mediated BET inhibition could suppress the transcription of several downstream oncogenes (e.g., BCL-2, C-Myc, and CDK-6) to inhibit tumor growth." (PMID 37328484, 2023). "In the study of The Cancer Genome Atlas Network for HNSCC, the percentages (%) of PTEN genetic alterations in HPV (+) and HPV (-) tumours were 12% and 6%, respectively, and either PTEN mutation or inhibition could result in PIK3CA/CCND1/CDK6 pathway activation and thereby enhance cell proliferation." (PMID 35421166, 2022). "Therefore, inhibiting the activity of CDK6 cells may affect the survival of tumor cells by inducing instability in the cell genome." (PMID 35480115, 2022). "Fourth, the CDK6 inhibitor molecules also have other functions that may prevent tumor occurrence." (PMID 35780240, 2022). "However, the efficacy was far less than the DOX-treated KB-C2-k.o.cdk6 tumor group." (PMID 35459184, 2022). "Moreover, the finding that GNAS copy number gain can markedly enhance tumor cell proliferation implied that an inhibitor therapy targeting CDK6 may be effective for PIT1 lineage patients harboring GNAS copy number gain." (PMID 36307579, 2022). "Loss of CDK6 in peripheral T cells did not affect tumor surveillance of MC38 tumors in vivo." (PMID 34248938, 2021). "Furthermore, our result indicated that miR-200a may inhibit tumor progression by interacting with CDK6 and ZEB1." (PMID 34796112, 2021). "The potential need for combined inhibition of CDK4 and CDK6 kinase activities represents another possibility that might explain why T cell-intrinsic CDK6-deficiency does not have an impact on anti-tumor immunity." (PMID 34248938, 2021). "To test whether the observed up-regulation of DNMT1 expression in ALK tumor samples is associated with deregulation of cell cycle–associated genes, we performed Western blot analysis using antibodies against c-MYC, CDK4/CDK6, cyclin D1, and the proliferation marker PCNA." (PMID 33310759, 2021). "In addition, we have shown that miR-29b-3p may be a tumor suppressor through repressing expression of CDK6, which is strongly involved in palbociclib sensitivity." (PMID 32934206, 2020). "CDK6 may exert tumor promoting and tumor suppressing functions." (PMID 33255177, 2020).
tumor (continued). "Interestingly, CDK4 gene expression was higher in luminal B and basal-like CCND1-amplified tumours only (“CDK4” P = 0.004 and P = 0.029 respectively) whilst CDK6 expression was lower in luminal A, luminal B and HER2-enriched CCND1-amplified tumours (“CDK6” P < 0.001 for all comparisons)." (PMID 30819233, 2019). "MiR-378 may exert tumor suppressor roles by deregulating the expression of CDK6 and VEGF in GC." (PMID 30619739, 2018). "To investigate whether validated targets of miR-34a were modulated by its synthetic mimic in DMPM cells, we assessed protein expression levels of c-MET, AXL, and CDK6 considering their established role in the control of cell proliferation and apoptosis in different tumor types." (PMID 28100259, 2017). "Thus, combined with the verified oncogenic role of NNT-AS1 in HCC, we could conclude that NNT-AS1 exert the tumor-promoting role via miR-363/CDK6 axis." (PMID 29179477, 2017). "Recent studies have documented localization of some tumor-related genes, such as CDK6, BRAF, and c-MET at the upstream/downstream domain of miR-183-96-182 cluster, suggesting that these genes might be regulated to process similar functions of tumor-related molecules." (PMID 27081087, 2016). "Our results showed that tumor cell-cell contact induced cell proliferation which may represent dormancy escape via activation of β1 integrin associated with universal downregulation of TGFB2 signaling and upregulation of MLCK activation/CDK6 in PCa PDXs." (PMID 26090669, 2015). "This notion was reinforced when tumor cells expressing wild-type Rb were found to have genetic and epigenetic alterations of the p16 tumor suppressor gene or oncogenic expression of cyclin D1, D2, D3, Cdk4, and Cdk6 genes, which became known as the ‘p16-cyclin D-Rb’ pathway." (PMID 24876129, 2014). "Armed with the genetic evidence of mutations involving KRAS and CDK6/CDK14 as well as the response to single agent therapies, we reasoned that treatment with a combination of drugs addressing the key mutations associated with propagation and metastasis in the CB42 should result in tumor regression." (PMID 25162504, 2014). "However, these restricted samples still provide statistically important information, which indicate the over-expression of CDK6 in the tumor margin may correlate with poor prognosis." (PMID 23594394, 2013). "CCND1 downregulation is well characterized to decrease activation of cyclin-dependent kinases Cdk4 and Cdk6, that are not only required for G1 to S phase transition during cell cycle progression but also are major players in interaction with stromal cells that sustain tumor growth." (PMID 24143218, 2013). "Thus, CDK6 may affect uncontrolled proliferation during tumor development by Rb-independent mechanisms and accordingly our study unraveled a novel connection between CDK6 and NF-κB." (PMID 23300567, 2012). "WB analysis revealed that FAM84A knockdown led to a decrease in N-cadherin, C-myc, CDK6, and Bcl-2 levels, while E-cadherin and Bax expression increased, indicating that FAM84A plays a critical regulatory role in tumor cell growth, metastasis, and apoptosis." (PMID 41179292, 2025). "In tumor tissue, the expression levels of miR-124 targets, including CDK4 and CDK6, were reduced in UMSCs expressing miR-124 group." (PMID 40134003, 2025). "Transcriptional analysis showed a marked downregulation of key genes involved in tumor cell growth and proliferation, including CDK1, CDK2, and CDK6 (up to a 31.11‐fold decrease), PLK1 (up to a 21.49‐fold decrease), and SKP2 (up to a 14.68‐fold decrease)." (PMID 41221154, 2025). "Compound 7p, in particular, displayed strong affinity for key cancer-related targets such as HSP90, IGF1R, HDAC2, CDK6, HDAC8, and PIK3CA, all of which are involved in tumour proliferation, survival, and metastasis." (PMID 41463373, 2025).
tumor (continued). "Consistently, there was a significantly positive correlation between the expression levels of CDK6 and IGF2BP3 in the IHC analysis of xenograft tumor model." (PMID 40083693, 2025). "miR‐206 directly targets CDK6 in the RAS signaling pathway, and its introduction into PM cells inhibits tumor growth; this effect is further enhanced when combined with the cyclin‐dependent kinases 4 and 6 (CDK4/6) inhibitor abemaciclib." (PMID 40904706, 2025). "Subsequently, tumor tissue proteins were extracted to detect the expression of the key EMT protein N-cadherin, the oncogenic protein C-myc, and the key G1 phase protein CDK6." (PMID 40006058, 2025). "Several cell cycle proteins, including D- and E-type cyclins, CDKs (CDK2, CDK4, CDK6), PLK1, and Aurora kinases, are commonly overexpressed in cancers and contribute to tumor development and progression." (PMID 41154590, 2025). "Another highly relevant activity for cancer progression is the ability of CDK4 and CDK6 to suppress senescence by phosphorylating FOXM1, maintaining cell cycle progression and preventing tumor suppressive mechanisms." (PMID 39800748, 2025). "In our case, the tumor specimen presented heterozygous deletions of CDKN2A, CDKN2B and CDKN2C, and gains of CDK6 and CCND2." (PMID 38369555, 2024). "CDK4 and CDK6 play a key role in mammalian cell proliferation by working in complex with CCND1 to phosphorylate and inhibit RB1 tumor-suppressor activity during early G1 phase." (PMID 38507413, 2024). "P16 functions as a tumor suppressor, acting through CDK4 and CDK6 to keep the retinoblastoma (Rb) gene product hypophosphorylated, hence inactivated, pausing the cell cycle." (PMID 38989391, 2024). "Preclinical studies have demonstrated that BRG1 inactivation increases tumor invasiveness and enhances sensitivity to targeted agents inhibiting oxidative phosphorylation and drugs targeting EZH2, AURKA, ATR, CDK4, and CDK6." (PMID 39465834, 2024). "IGF2BP2 overexpression in LSCC promotes the CDK6 mRNA stability and protein expression, thus increasing the expression of CDK6 and promoting LSCC cell proliferation and invasion in vitro and tumor growth in xenograft tumor models." (PMID 39403369, 2024). "The multivariate analysis included tumour stage and CDK4, CDK6, CDK2, cyclin D1, cyclin E1, RB1 and pRB1 protein expression." (PMID 38612869, 2024). "This suggests a potential therapeutic strategy combining CDK4/CDK6 inhibitors with SETDB1 and TRIM28 modulators to stabilize pRB and suppress tumor growth." (PMID 39664374, 2024). "All tumor samples revealed positivity for CDK4, CDK6 (except in one patient), Rb, and pRb, reinforcing cell cycle deregulation." (PMID 39411551, 2024). "For example, CDK4, CDK6, and CDK7 can influence immunotherapy efficacy by affecting the tumor microenvironment (TME)." (PMID 39371450, 2024). "In Community 1-related immune genes, Cdk6 and Havcr2 are robustly expressed in the exhaustive CD8 T cells, playing roles in connecting EMT and tumor immune." (PMID 38331768, 2024). "Our study showed that knockdown of eIF3a reduced the CDK4 and CDK6 expression in DLBCL cells, suggesting that targeting eIF3a has a potential anti-tumor effect in DLBCL." (PMID 38589831, 2024). "Tumor tissues from CDK4/6i monotherapy showed higher protein levels of LRPPRC and CDK6 compared to the control group, indicating the activation of the LRPPRC-CDK6 feedback loop after CDK4/6i treatment in vivo." (PMID 37452037, 2023). "In this tumor type, CDK6 and FGFR2 were less expressed than in normal tissue, whereas CDK7, MET, ALK and AURKB stood out as upregulated in tumor samples." (PMID 36839989, 2023). "miR-3174 downregulated the expression of multiple tumor-promoting genes including CD44, MDM2, RHOA, PLAU and CDK6." (PMID 37298284, 2023). "LncRNA NEAT1 participates in tumor differentiation, metastasis and TNM staging of CRC via NEAT1/miR-495-3p/CDK6 axis." (PMID 38309281, 2023).
tumor (continued). "EA specifically interferes with several signaling cascades, including PI3K/AKT, NF‐B, CDK6, TGF‐/Smad3, and AKT/mTOR, to perform its anti‐tumor actions." (PMID 38107139, 2023). "Pemigatinib treatment also caused the upregulation of microRNAs (miR-133b, miR-139, miR-186, miR-195) with tumor suppressor functions, along with the downregulation of validated protein targets with oncogenic roles (c-Myc, c-MET, CDK6, EGFR)." (PMID 37715207, 2023). "Further, we also demonstrated that miR-3174 downregulates multiple tumor-promoting genes (CD44, MDM2, CDK6, RHOA and PLAU) and all of these have been reported to have an important role in the development of various malignancies, including GBM." (PMID 37298284, 2023). "The tools predicted several tumor-promoting genes as a potential target of miR-3174 including CD44, CDK6, MDM2, RHOA and PLAU." (PMID 37298284, 2023). "To further confirm CDK6 overexpression in HCC, we used a tissue microarray consisting of 51 HCC samples and the corresponding matched non-tumor liver tissue samples to evaluate CDK6 expression by immunohistochemical staining." (PMID 37872167, 2023). "Similar results were noted for the tumor regulation signatures differentiation and RB1, high GEX of CDK6, and PTEN, and signatures related to tumor immune activity and inhibitory immune signaling." (PMID 37773134, 2023). "Bioinformatics analysis and sequence alignments performed in our laboratory proposed that miR-3174 can target many influential tumor-promoting genes involved in the pathobiology of GBM, including CD44, PLAU, MDM2, CDK6 and RHOA." (PMID 37298284, 2023). "CCND1 forms complexes with CDK4 or CDK6 as a regulator of CDK kinases, and its tumor-promoting role has been intensively investigated in human cancers." (PMID 37770914, 2023). "It has been reported that the downregulation of CDK6 also suppresses its interacting gene, RB1—a tumor suppressor gene." (PMID 37900178, 2023). "The expression levels of MCM7, CDK6 and POLA1 showed a remarkably elevated trend according to the grade of the tumor, and differences between all grades were statistically significant." (PMID 37005685, 2023). "RB1 is a tumor suppressor that is inactivated by phosphorylation by a complex of CDK4 and CDK6 with cyclin D." (PMID 36003783, 2022). "Tumor enlargement was most rapid in DOX-untreated KB-C2 group, followed by DOX-treated KB-C2 and DOX-untreated KB-C2-k.o.cdk6 groups." (PMID 35459184, 2022). "We next used immunohistochemistry to validate the expression of cleaved caspase-3, CDK6, γH2A.X, BCL-XL and BIM in tumor masses." (PMID 35799216, 2022). "By contrast, when both CDK6 and CDK4 are coexpressed in a tumor at comparable levels, CDK6 drives Rb/E2F output." (PMID 36051751, 2022). "By knocking down cdk6 in KB-C2 cell population, metastasis and survival of KB-C2-k.o.cdk6 tumor cells were remarkably inhibited in the DOX-treated nude mice, mainly because the drug resistance of KB-C2-k.o.cdk6 was inhibited compared with KB-C2." (PMID 35459184, 2022). "The pivotal genes CDK6 and MET of the T. hemsleyanum-inhibited tumor were confirmed, providing a new theoretical basis for the clinical application of T. hemsleyanum." (PMID 35480115, 2022). "Because metabolic pathways are often subverted in tumor cells, the roles that CDK4 and CDK6 play in malignant cell metabolism as it relates to cell survival is an active area of research." (PMID 36051751, 2022).